IL6 (interleukin 6)
Diseases named in the same sentence as IL6 in open-access papers (continued):
Sharing a sentence is not in itself a finding about the gene and the disease.
cancer (continued). "A2M’s role in cancer biology is likely due to its ability to act as a signalling molecule and transporter of growth factors, such as TGFβ and IL6, and as a modulator of protease activity." (PMID 32927694, 2020). "Significantly enough, cancer epithelial cells in the bone produce several inflammatory factors, such as IL-6, IL-8, TNF-α, and CCL2, which continue to promote immune evasion and interfere with normal bone forming and resorption processes." (PMID 33076397, 2020). "Metastatic cancer cells, besides releasing numerous paracrine factors, e.g., parathyroid hormone-related peptide (PTHrP) and interleukin 6 (IL-6), also affect the immune system, vascular endothelium, nerve cells, and platelets." (PMID 33396969, 2020). "It has been demonstrated that IL-6 can induce STAT3 to ensure the malignant behavior of cancer cells." (PMID 32545648, 2020). "IL-6 is an important mediator which secretes from cancer cells in high concentrations and highly promotes tumorigenesis and protects the cancer cells from therapy-induced DNA damage, oxidative stress, and apoptosis by inducing several pathways." (PMID 33426090, 2020). "Soluble factors secreted by cancer cells, such as IL-6, have been recently found to acquire pro-tumoral functions by stimulating the pro-survival activities of stromal cells, thereby contributing to cancer progression." (PMID 32325830, 2020). "Both in ageing-related and cancer-induced cachexia, IL-6 alone, or in combination with other factors, plays a critical role." (PMID 33114676, 2020). "Our data demonstrated that IL-6 was significantly increased after MWA treatment, IL-6 is derived from monocytes, macrophages, DCs, Th2 cells and sometimes cancer cells, and it plays a key role in T cell proliferation and survival." (PMID 32847533, 2020). "NFs have a profound impact on ccRCC migration and accelerate the cancer invasion and metastasis, which was mainly through a IL6-induced STAT3 activation." (PMID 31636361, 2020). "Conversely, Th2 cells demonstrate pro-cancer function via the secretion of interleukin-4 (IL-4), interleukin-6 (IL-6), interleukin-10 (IL-10), and transforming growth factor-β (TGF-β)." (PMID 32370060, 2020). "MAPK signaling pathway can inhibit T cell immune response by enhancing the expression of immunomodulatory cytokines IL-6 and IL-10, which play a key role in cancer immune escape." (PMID 33344447, 2020). "IL6 is produced by many different cells, e.g., macrophages, T and B cells, endothelial cells, adipocytes, and various cancer cells." (PMID 33066437, 2020). "According to the present study, it seems that red clover extract can decrease the proliferation and viability of cancer cells by decreasing serum levels of inflammatory cytokines, especially IL‐6." (PMID 33133558, 2020). "IL6-JAK-STAT3 pathway is known to be implied in tumorigenesis and play a role in cancer-associated inflammatory environment and angiogenesis." (PMID 32659965, 2020). "Our group has previously reported that a lipid mediator, S1P, links inflammation and cancer due to the amplification loop of IL6 and NFkB." (PMID 33457427, 2020). "Produced by macrophages but secreted mainly by tumor cells, IL-6 is able to increase muscle cells autophagy in murine models of cancer and affect cachectic patients’ body composition by targeting adipose tissue, gut, and liver tissue." (PMID 33202621, 2020). "IL-6 is a pro-inflammatory cytokine that has a pivotal role during chronic inflammation and cancer development." (PMID 32326073, 2020). "IL6, one of the mediators of the immune/inflammation response and inducers of EMT, can increase cancer-associated stemness and MMP activity and M2 macrophage polarization via the MCT-1/miR-34a/IL-6/IL-6R signaling pathway." (PMID 32268506, 2020). "IL-6 participates in the development of inflammation in the course of many cancers: breast, prostate, colon, lung, stomach and brain." (PMID 33327591, 2020).
cancer (continued). "Research emphasizes the critical role of humoral factors secreted by cancer cells in the patient’s tissues in the regulation of processes leading to cachexia, which also include pro-inflammatory cytokines IL-6, TNF-α, IFNγ, IL-1α, and IL-1β." (PMID 33158194, 2020). "Studies have also demonstrated that USP24 promotes cancer malignancy by inducing IL-6 transcription into tumor-infiltrating leukocytes, vascular endothelial cells, and cancer-associated fibroblasts." (PMID 32354135, 2020). "IL-11 or IL-6 inhibitors displayed potent anti-cancer activity in pre-clinical models of cancer of distinct origins." (PMID 33553157, 2020). "Pro-inflammatory cytokines such as TNFα, IL-6, and IL-8, which are frequently elevated in cancer patient serum samples, are also involved in both platelet activation and autophagy." (PMID 33365273, 2020). "As well, we identified several proinflammatory cytokines such as IL-1 alpha, IL4, IL6, LIF, TNF which have been implicated in cancer cachexia." (PMID 33334063, 2020). "Previously, the NF-κB-Lin28-let-7-IL-6 positive feedback loop links inflammation to cancer and maintains cells at an epigenetic transformed state, suggesting that IL-6 is an important target gene of let-7f." (PMID 32133007, 2020). "TAMs greatly contribute to the aggressive progression of cancer by releasing cell-stimulating growth factors and cytokines, including IL-6, IL-10, and TNF-α." (PMID 32222879, 2020). "The abundance of Corynebacterium_1 was previously demonstrated to be correlated with serum concentrations of interleukin-6 and C-reactive protein in cancer patients." (PMID 32508748, 2020). "IL-6 families were playing important function in the regulation of initiation, progression and recurrence of human cancers." (PMID 32552789, 2020). "Previous studies have shown that phosphorylation and degradation of the IκBα protein promotes the activation of NF-κB and the expression of TNF-α, IL-1β, and IL-6, participating in the formation and development of cancer pain." (PMID 32431607, 2020). "A recent study has shown that neural adhesion molecule L1 promotes EC proliferation and migration through the IL-6/JAK/STAT axis, and IL-6-mediated STAT3 phosphorylation is associated with EndMT and promotes cancer growth." (PMID 32296578, 2020). "IL-6 levels are correlated with cancer progression and inversely correlated with patient response to treatment and survival." (PMID 32422889, 2020). "The serum of elderly patients with chronic disease or cancer usually contains more IL-6 than the serum of young healthy people." (PMID 33383723, 2020). "Among the signaling pathways, STAT-3 is the main transactivator downstream of IL-6 signaling, and IL-6 is involved in the activation of oncogenic STAT-3 in many kinds of cancer." (PMID 32855767, 2020). "In parallel to its key role in immune-mediated inflammation, IL-6 sustains tumorigenesis both through a direct stimulation of cancer cells and through an indirect action on the TME." (PMID 33194755, 2020). "Gp130 has been implicated as the main cellular receptor in skeletal muscle to mediate the IL-6 effects in cancer cachexia." (PMID 33329046, 2020). "As a primary mediator of the inflammatory response, IL-6 is very important in the pathogenesis of many types of cancer." (PMID 32878114, 2020). "Bioinformatics analysis exhibited that the changed cytokines were mainly enriched in cancers signaling pathways and interleukin-6 (IL-6) was located in the core of the integrated network." (PMID 32134471, 2020). "Decreased levels of IL-6 (which counters the apoptosis induced by chemotherapy) and high IL-6 levels (which negatively impact cancer prognosis) have also been observed." (PMID 32595757, 2020). "The principal pro-inflammatory cytokine IL-6 can promote tumor progression via inhibition of cancer cell apoptosis as well as promotion of angiogenesis." (PMID 33162990, 2020).
cancer (continued). "The dysregulation of miRNA in BCAFs can also interfere with the production of paracrine signalling factors such as TGF-β1 and IL-6 to influence cancer progression, metastasis, and drug resistance." (PMID 33066013, 2020). "Similar results were achieved using an IL-6 neutralizing antibody, all posing potential therapeutic targets to diminish the effects of fibroblasts-induced cancer promotion and growth in the GC microenvironment." (PMID 32268527, 2020). "Interleukin 6 (IL6) encodes a cytokine involved in inflammation and located in a wide variety of inflammation-associated diseases, some of which lead to cancer development (RefSeq: NG_011640.1)." (PMID 32649728, 2020). "Elevated IL-6 activates proliferation of cancer cells directly, accelerates angiogenesis and promotes binding to other organs." (PMID 33351844, 2020). "The IL-6/JAK2/STAT3 signaling pathway is currently the central object of research on cancer cachexia." (PMID 33158194, 2020). "IL-6 is a multifunctional cytokine served as an important regulator of inflammation and involved in protumorigenic activities, including cancer cell proliferation, angiogenesis stimulation, and immune tolerance." (PMID 32595734, 2020). "In particular, IL-6 is an important mediator of CRP production and is associated with cancer cell growth; CRP correlates to IL-6 concentrations in tumors." (PMID 32309219, 2020). "And the inflammatory cytokines such as interleukin-6, transforming growth factor-beta, tumor necrosis factor-alpha, and platelet-derived growth factors are also an important factors of cancer pathogenesis." (PMID 31980025, 2020). "In HBV-related cancers, Oct4 is a marker of poor prognosis and has been shown to be upregulated via the IL-6 pathway." (PMID 32298395, 2020). "Compared with IL-6 classic signaling, trans-signaling shows a different spectrum of IL-6-mediated actions, which is mainly involved in inflammatory diseases and cancer progression." (PMID 32070329, 2020). "This correlation with IL-6 is consistent with a large body of literature from human studies suggesting that IL-6 adversely impacts cancer extent of disease and prognosis." (PMID 32084139, 2020). "Since previous studies have reported that interleukin-6 (IL-6) was a precancerous cytokine, which can promote the migration of cancer cells, this study also tried to check the role of IL-6 in the interaction between HSCs and cancer cells." (PMID 33346211, 2020). "Tumors are heterogeneous and regulate dynamic reaction between BCSCs and cancer cells by extracellular IL-6 and IL-8." (PMID 33202749, 2020). "Some myokines, such as decorin, IL-6, irisin, oncostatin-M, have been found to play a role in cancer modulation." (PMID 31936342, 2020). "In primary squamous lung cancer, statins break the communication between cancer cells and mesenchymal stromal cells (MSCs) by inhibiting CCL3 secreted by cancer cells and IL-6 and CCL2 produced by MSCs." (PMID 32843638, 2020). "IL-6 plays a pivotal role in linking chronic inflammation to cancer initiation, growth and metastasis." (PMID 32423132, 2020). "Excessive IL-6 production and dysregulation of the IL6/IL6R axis can lead to inflammation or cancer." (PMID 32957689, 2020). "Apart from the morphological changes, the expression of surface markers on the IL-6-treated cancer cells almost reduced to half." (PMID 33659239, 2020). "The enriched cancer hallmarks in low-risk group, including the interferon alpha (IFN-α) response, the interferon-γ (IFN-γ) response, IL-2/STAT5 signaling, IL-6/JAK/STAT3 signaling, epithelial mesenchymal transition, TGF-β signaling and hedgehog signaling." (PMID 32850356, 2020). "In conclusion, our data demonstrate how the cancer education of naive fibroblasts influences the circadian parameters of neighbouring cancer cells and highlights a putative role for IL6 as a novel candidate for preoperative treatments." (PMID 32341349, 2020).
cancer (continued). "Cancer cells through chemokines secretion can convert adipocytes into their activated form Cancer-Associated Adipocytes (CAAs), that has been reported to promote IL-6-mediated EMT in cancer cells." (PMID 32266157, 2020). "The function of IL-6 has been explored in facilitating chemoresistance in various cancers in previous studies." (PMID 32391256, 2020). "Since both FAS and IL6 were closely associated with cancer pathogenesis and STAT3 activation, we investigated IL6 mRNA and protein levels after FAS knockdown." (PMID 32963220, 2020). "This review found several information about IL-6 protein including 48 publications that investigate IL-6 as a cancer biomarker in 5316 individuals with GIT cancer." (PMID 32961987, 2020). "Increased cytokine interleukin-6 and leptin lead to elevated CYP1B1 activity, which possibly causes cancer." (PMID 32626511, 2020). "Consistent with an autocrine function of activin A in the regulation of IL‐6 secretion from the cancer cells, an activin A neutralizing antibody reduced the level of IL‐6 in CMs by 22% from 6.1 ng/mL in untreated cells." (PMID 31436048, 2020). "It is well-known that IL-6 drives many “hallmarks” of cancer through downstream activation of the Janus kinase/signal transducer and activator of transcription 3 (JAK/STAT3) signaling pathway." (PMID 32373541, 2020). "Another interesting observation was that patients who were removed from the study due to toxicity had higher levels of interleukin-6 (IL-6) at all time points compared to patients who were removed due to progression of cancers." (PMID 32019149, 2020). "Pro-inflammatory cytokines, such as leukemia inhibitory factor (LIF) and interleukin-6 (IL-6), are secreted by both cancer cells and CAFs, and mediate the epigenetic modification of CAFs." (PMID 32546182, 2020). "In summary, the IKKβ/NF-κB signaling pathway and the pro-inflammatory cytokines TNF-α, IL-1β, and IL-6 play important regulatory roles in the development of cancer pain." (PMID 32431607, 2020). "IL-6 neutralization significantly cancelled the ability of cancer cells migration and proliferation induced by aHSC-CM, compared with Immunoglobulin G (IgG) as a control." (PMID 33346211, 2020). "For example, tumor necrosis factor-alpha (TNF-α) and interleukin 6 (IL-6), the main cytokines released during chronic inflammation, are known to stimulate proliferation of cancer cells, their survival and their dissemination." (PMID 33013813, 2020). "Stimulated by cytokines including GM-CSF and IL6, C/EBPβ plays an indispensable role in emergency granulopoiesis and expansion of MDSCs in cancer." (PMID 33081041, 2020). "It has been shown that the interaction between astrocyte and MDA-MB-231 cells induced the production of IL-6 and IL-8 by cancer cells." (PMID 33322216, 2020). "Circulating IL-6 levels have been verified to be a prognostic indicator of survival in several different types of cancers and a predictor of the response to treatment." (PMID 33363013, 2020). "We chose to validate the change of IL-6 and VEGF for their key roles in cancer metastasis and association with metastatic breast cancers." (PMID 32005799, 2020). "This conclusion agrees with our data showing an increase of IL-6 levels in the supernatant of normal and cancer cells incubated with the conjugate." (PMID 33321722, 2020). "A similar phenomenon during the adipocyte and cancer cell co-culture was observed for the pro-inflammatory cytokines IL-6, IL-1β, IL-8, and for the fatty acid-binding proteins (FABPs), which was found to promote homing, migration, and invasion of cancer cells." (PMID 32015297, 2020). "Although all these studies differed in murine models and cancer cells used, the therapeutic paradigm of targeting IL-6 pathway at the early stages of metastasis formation is promising." (PMID 33322216, 2020).
cancer (continued). "Although studies about cancer cells showed remarkable correlation between IL-6, chemoresistance, and increased proliferation, as well as IL-6 to be used as a therapeutic target, they are all currently being investigated." (PMID 32961987, 2020). "The increased circulating CRP and IL-6 along with reduced CYP3A4 activity observed in a subset of cancer patients indicates the role of IL-6 as being a potential mediator in the process." (PMID 33076284, 2020). "As a result, we considered IL6 as the most likely paracrine factor that contributes to the enhanced cancer cell migration and invasion." (PMID 32308766, 2020). "Cancer cells are also able to produce many proinflammatory cytokines like IL-1 and IL-6, which stimulate the formation of CRP in the liver." (PMID 30828780, 2020). "Research has suggested that the IL-6 signaling pathway plays an important role in the development and chemoresistance of various cancers, including CRC." (PMID 33198757, 2020). "It is well known that IL-6 promotes cancer cell growth, invasion, migration, and epithelial-mesenchymal transition (EMT), resulting in prostate metastasis." (PMID 32971847, 2020). "Bioinformatics analysis showed these differentially cytokines were mainly enriched in cancer signal pathways and IL-6 is the most critical hub in the integrated network." (PMID 32134471, 2020). "Cachexia is characterized by the activation of systemic inflammation, which is reflected by increased serum levels of C-reactive protein; however, the catabolic drive during cancer cachexia can also be reflected by other cytokines, including IL-6 and TNFα." (PMID 32708527, 2020). "The most prevalent mechanism of STAT3 activation in cancer is via the pro-inflammatory cytokine IL-6." (PMID 32899142, 2020). "TAM-derived IL6-mediated STAT3 signaling pathway also found to increase the proliferation of human cancer stem cells." (PMID 32219066, 2020). "In a recently published study, the level of T regs in human bladder tissue significantly correlated with both TAMs and with IL-6-positive cancer cell count." (PMID 31811337, 2020). "NLRP3 and IL1B were upregulated in cancer tissue compared to normal, while IL6 expression was unaltered." (PMID 32630814, 2020). "This analysis indicated that the biological category “Pathways in cancer” is the most enriched for IL-10 targeted genes and “Cytokine-Cytokine receptor interaction” for the IL-6 targeted genes." (PMID 32211606, 2020). "IL-6 is a known protumoral cytokine favoring cancer cell formation and disease progression, which has also been associated with dexamethasone resistance and plasma cell retention in BM." (PMID 33383723, 2020). "Increased expression of IL-6 correlated with decreased sensitivity to doxorubicin treatment in cell lines representing all cancer types." (PMID 32528731, 2020). "The IL-6/JAK2/STAT3/MMP-9 pathway has been described in a variety of human cancers and plays an essential role in microvessel proliferation and BM degradation." (PMID 32047820, 2020). "Activated CAFs promote cancer progression by secreting pro-inflammatory cytokines, including IL-6 and IL-8." (PMID 32466591, 2020). "The IL-6/JAK/STAT3 pathway is overactivated in many cancer patients, and numerous studies involving preclinical in vitro and in vivo models have shown that targeting a single nodule in this pathway can have antitumor effects." (PMID 33363013, 2020). "Enhanced cancer cell growth rates and invasiveness in an IL-6-dependent manner (through activation of Notch-3, Jagged-1, and CAIX via STAT-3) was reported by Studebaker." (PMID 32707920, 2020). "IL-6 plays an important role in the development and progression of inflammatory responses, autoimmune diseases, and cancers." (PMID 32209102, 2020). "Several studies showed that MDSCs promote cancer cell stemness through inducing miRNA, production of IL-6 and NO, inducing piRNA-823 expression and DNMT3B activation." (PMID 32391020, 2020).